ALDH1A1 (aldehyde dehydrogenase 1 family member A1)
Diseases named in the same sentence as ALDH1A1 in open-access papers (continued):
Sharing a sentence is not in itself a finding about the gene and the disease.
tumor (continued). "They proposed that ALDH1A1 high/CD44 low/EGFR low tumor cells may be stationary and quiescent, while ALDH1A1−/CD44 high/EGFR high cells may be invasive and migratory." (PMID 34359786, 2021). "Interestingly, ALDH1A1+ BCSCs that co-expressed Notch1 showed direct contact with the tumor endothelium that expressed DLL4 in a tumor arteriole." (PMID 34168243, 2021). "Finally, ZEB1, BMI1, and ALDH1A1 were highly expressed in tumor specimens from EGFR‐mutant NSCLC patients with gefitinib resistance." (PMID 33764690, 2021). "Notably, immunostaining for ALDH1A1 in the xenograft tumor tissue was heterogenous, indicating random niches of tumor cells having stem cell-like phenotype." (PMID 34493733, 2021). "Moreover, a significant decrease in the expression of DLX1 target, ALDH1A1 was also recorded in DLX1-KO tumor tissues." (PMID 34493733, 2021). "The study of Liu and colleagues demonstrated that the expression of ALDH1A1 mRNA, one of predicted target mRNAs, in tumor tissues may be an independent predictor of TNBC outcome." (PMID 33753785, 2021). "In addition, there was positive correlation between the expression of CCR9 and ALDH1A1 in the same tumor microenvironment." (PMID 32308544, 2020). "Additionally, ALDH1A1 promoted tumor angiogenesis via retinoic acid/HIF-1α/VEGF signaling, while being identified as an indication for poor CRC outcome." (PMID 32630086, 2020). "EGCG treatment inhibited tumour sphere formation and ALDH1A1 and SNAI2 (Slug) expression." (PMID 32051483, 2020). "Similarly, a study with thyme haulm showed a significant decrease in CD44 and ALDH1A1 expression in tumor tissues in rats." (PMID 32204409, 2020). "Furthermore, the expression of ALDH1A1+ CSCs in the same tumor microenvironment was detected using serial paraffin-embedded sections." (PMID 32308544, 2020). "In this section, we describe the effects of ALDH1A1 in stemness phenotype tumor angiogenesis, tumor metastases, antitumor drug resistance, and immune evasion, hypothesizing its central role in tumor malignancy." (PMID 35582039, 2020). "We then explored how dying tumor cell-derived exosomes promoted survival of the ALDH1A1+ cells." (PMID 32228703, 2020). "Besides, the expression of CCR9 was positively correlated with ALDH1A1 expression in the same tumor microenvironment." (PMID 32308544, 2020). "Furthermore, within this amoeboid tumour-initiating phenotype, we identify ALDH1A1, a key gene for tumour-initiating abilities." (PMID 33082334, 2020). "These pre-clinical data were further supported by the analysis of double-marker immunofluorescence in human TNBC cases that allowed us to reveal the intra-tumor coexistence of neoplastic elements co-expressing both ALDH1A1 with PD-L1 and CD44v6 with PD-L1 biomarkers." (PMID 30705400, 2019). "Similarly, in colorectal cancer cells, PrPc overexpression is accompanied by the upregulation of the stemness markers Oct4, Nanog, Sox2, and ALDH1A1, which is correlated with tumor growth, proliferation, and angiogenesis." (PMID 31618844, 2019). "For S15, ALDH1A1 expression was comparable in culture and in the original tumor." (PMID 31181618, 2019). "Likewise, siRNA-mediated ALDH1A1 knockdown reduced OC cells’ proliferation as spheres, expression of stemness markers, and delayed tumor initiation capacity in vivo." (PMID 30965686, 2019). "Additionally, both PD-L1-/SCA1-positive and ALDH1A1-positive tumor elements were found in close contact with CD3-, and PD-1-positive T cells in murine and human tumor samples." (PMID 30705400, 2019). "The median time to tumor initiation defined as the time between tumor cell inoculation and formation of detectable tumors was 27 days for sh-control cells and 33 days for sh-ALDH1A1 OVCAR3 cells (p = 0.003), suggesting that this isoform plays a functional role in OC cell tumorigenicity." (PMID 30965686, 2019).
tumor (continued). "Moreover, ALDH1A1 mRNA levels were increased in tumor tissue obtained from colon carcinoma tumor-bearing mice treated with a combination of leucovorin, 5-fluorouracil, and irinotecan (FOLFIRI) compared to non-treated mice." (PMID 30308036, 2018). "Additionally, we also checked the expression of stem cell markers (SOX2 and aldehyde dehydrogenase 1 family, member A1 (ALDH1A1)) in the tumor samples." (PMID 30150594, 2018). "Moreover, exposure to the enzyme inhibitor CM037 significantly reduced VEGF expression and release, suggesting that the level of ALDH1A1 expression and activity is critical for the development of an aggressive tumor phenotype." (PMID 30541574, 2018). "Since VEGF transcription is induced by HIF-1α in tumor cells, we also sought to determine whether ALDH1A1 regulates HIF-1α transcriptional activation in MCF-7 cells." (PMID 30541574, 2018). "High levels of ALDH1A1 were associated with a poorly differentiated histology and a right-sided tumor location, but not to a mesenchymal-like molecular subtype." (PMID 30308036, 2018). "Finally, the expression of stemness markers SOX2 and OCT-4 was increased as mRNA level in tumor enriched with ALDH1A1." (PMID 30541574, 2018). "Radio- and/or chemotherapy prior to tumor resection was associated with increased ALDH1A1 levels regardless of the molecular subtype." (PMID 30308036, 2018). "ALDH1A1 expression or activity may be used with other cell surface markers to identify tumor-initiating cells in hepatocellular, prostate and breast solid carcinomas." (PMID 29299137, 2017). "Furthermore, SOX9 knockdown suppressed tumor metastasis and the expression of the stem cell marker ALDH1A1." (PMID 28912540, 2017). "Additionally, overexpression of miR-218 inhibited ALDH1A1 positive to survive in anchorage-independent conditions and their ability to form tumor-spheres." (PMID 28830450, 2017). "Re-introducing either ALDH1A1 or ALDH3A1 into cells restored the tumor growth in xenografts." (PMID 28978015, 2017). "Mice implanted with tumor cells had higher ALDH1A1 protein contents." (PMID 29245988, 2017). "Recent reports implicate ALDH1 and specifically its isotype ALDH1A1 as a useful CSC marker that could be used to enrich tumor-initiating subpopulations from various cell lines and primary tumors." (PMID 26783961, 2016). "In our study we have also characterized the malignant phenotype of the OSA3-CSCs by the analysis of the activity and the expression of aldehyde dehydrogenase 1 family, member A1 (ALDH1A1) a detoxification enzyme, which is responsible for the tumor resistance to cytotoxic chemotherapy." (PMID 27651797, 2016). "In primary NPC tissues, ALDH1A1 was intensely expressed in the cytoplasm of NPC tumor cells." (PMID 27647953, 2016). "Moreover, ALDH1A1-positive cells were barely detectable by immunohistochemistry in sections of Folfiri-treated tumor xenografts in the shPXR group compared to control group." (PMID 27448961, 2016). "In summary, our data indicate that tumor tissue ALDH1A1 mRNA expression level may be an independent biomarker of prognosis in TNBC patients." (PMID 26462023, 2015). "The ALDH1A1-high group was significantly associated with low serum levels of α-fetoprotein (AFP) (P = 0.0168), small tumor diameter (P = 0.0019), very little lymphovascular invasion (P = 0.0208), more differentiated pathology (P = 0.016) and good stage (P = 0.0215)." (PMID 26160842, 2015). "Our results suggest that ALDH1A1 mRNA expression in tumor tissue may be an independent predictor of TNBC recurrence and mortality." (PMID 26462023, 2015). "Thus, Aldh1a1 knockdown in sh-AhR cells (sh-AhR + sh-Aldh1a1) diminished their migration and invasion potentials and blocked tumor growth and metastasis to the lungs in immunocompetent AhR+/+ recipient mice." (PMID 26242870, 2015). "Moreover, co-expression of nuclear DKK-1 and cytoplasmic ALDH1A1 was demonstrated in the same tumor cells." (PMID 25788273, 2015).
tumor (continued). "We first examined if single Aldh1a1 knockdown affected tumor formation in AhR expressing cells." (PMID 26242870, 2015). "Instead, drug-induction suggested decrease for ITGB1/CD29c and ALDH1B1, while CD24, CD44, CD166, ALDH1A1 and Lgr5 were unchanged as detected by signals from microarrays with pooled tumor RNA from indomethacin-treated patients versus pooled tumor RNA from control patients." (PMID 25340937, 2014). "For example, the positive correlation between ALDH1A1 expression and the tumor size only could be found in the cutoff >0/1%, Asia, NA, and BD subgroups." (PMID 24938375, 2014). "ALDH1A1 plays an important role in tumor aggressiveness and prognosis, and may act as a promising target for prognostic prediction." (PMID 25253129, 2014). "In addition, a significant correlation between ALDH1A1 expression in the primary tumor and in the corresponding metastatic lymph nodes has been observed." (PMID 24938375, 2014). "ALDH1A1 staining mainly located in cytoplasm of tumor cells." (PMID 25253129, 2014). "However, our results revealed that high expression of ALDH1A1 correlated with larger tumor size, especially in the cutoff >0/1%, Asia, NA, and BD subgroups." (PMID 24938375, 2014). "Similarly, the expression of gene markers of tumor-initiating cells (ALDH1A1, CD29, INPP5D) was different between the CL subtype and the other subtypes, including the basal subtype (data not shown)." (PMID 25277734, 2014). "ALDH1A1 is a CSC marker for certain tumor entities and confers resistance to cyclophosphamide." (PMID 24212669, 2011). "Furthermore, we observed strong expression of ALDH1A1 more frequently in well-differentiated tumour samples." (PMID 21708005, 2011). "ADLH1A1 positivity was significantly associated with high tumour grade in ER- disease only, with 43% of ALDH1A1 positive tumours being grade 3 compared to 20% of ALDH1A1 negative tumours (P = 0.012)." (PMID 22112299, 2011). "Moreover, high expression of ALDH1A1 correlated significantly with the proliferation of tumour cells." (PMID 21708005, 2011). "However, by evaluating whole-mount tissue slides, we found ALDH1A1 to be expressed very heterogeneously within the tumour bulk." (PMID 21708005, 2011). "Second, we observed that claudin-low tumors compared to the other tumor subtypes, except for the normal breast-like group, showed the highest mRNA expression of ALDH1A1, which has recently been proposed to be another marker of breast stem cells and TICs but also noted in stromal cells." (PMID 20813035, 2010). "Furthermore, ALDH1A1 was expressed also in the distant brain metastases and the primary tumour taken from patients #1 and #5, respectively." (PMID 20505780, 2010). "In agreement with results observed in vitro with the ALDH1 inhibitor, DEAB, shRNA targeting of ALDH1A1 gene expression appeared to sensitize tumors to CPA in vivo, as tumor growth essentially stopped, whereas ALDH1A1-targeted shRNA cells treated with vehicle continued to grow (black triangles)." (PMID 18560594, 2008). "Finally, the dual role of ALDH1A1 in both tumor cells and the tumor microenvironment might lead to complex interactions that are not yet fully understood 44,45." (PMID 39744576, 2025). "Silencing ALDH1A1 expression could detriment the tumor-promoting effect of IL-8." (PMID 40008905, 2025). "To validate whether the expression of ALDH1A1 and ALDH1A3 genes also correlates with tumor radioresistance in PCa patients, we analyzed the expression of these genes in tumor tissues of patients with intermediate or high-risk localized PCa treated with radiotherapy (n = 67, Dresden cohort 9)." (PMID 38169509, 2024). "The results showed that the expression of ALDH1A1 was not significantly different in terms of age, gender, tumor staging, lymph node metastasis, and distant metastasis (P > 0.05), but it was associated with tumor diameter (P < 0.05)." (PMID 38589907, 2024).
tumor (continued). "Furthermore, an exploration into whether ALDH1A1 impacts the anti-tumor efficacy of the immune system was undertaken." (PMID 39107297, 2024). "Moreover, the distribution of ALDH1A1 in normal and tumor prostate tissues is quite distinct." (PMID 39796106, 2024). "Tumor organoids are 3D structures derived from human tumor tissues, they can anatomically and functionally mimic the tumor from which they were derived, and can enable us to determine the therapeutic potential of the ALDH1A1 inhibitor in a more clinically relevant fashion." (PMID 37429899, 2023). "Both murine SCC VII and primary human tumor cells collected from patients with HNSCC responded similarly in vitro to Rho kinase inhibition, which promoted a CD44hi tCSC phenotype additionally associated with coexpression of other stem cell markers including ALDH1A1, EpCAM, and EGFR." (PMID 37655661, 2023). "Moreover, patients with high ALDH1A1 expression had a higher degree of tumour differentiation." (PMID 36651035, 2023). "If this is true, then targeting ALDH1A1 in AML may sensitize tumor cells to chemotherapy." (PMID 37761947, 2023). "In addition, immunohistochemical analysis of the expression levels of NSE, NBL1, and ALDH1A1 in the tumor tissues of patients with SCLC showed that the expression level of NSE was positively correlated with that of ALDH1A1 and negatively correlated with that of NBL1." (PMID 35487890, 2022). "Moreover, there was a positive correlation between NSE and ALDH1A1 expression in tumor tissues." (PMID 35487890, 2022). "Therefore, we sought to detect the expression of SOX2, CD44, and ALDH1A1 in CxSCC tumor buds." (PMID 35860042, 2022). "Furthermore, we found that CD44 and ALDH1A1 were strongly expressed in tumor buds." (PMID 35083162, 2021). "Finally, in vivo experiments on nude mice comparing the vascularity development as well as other changes (VEGF intratumoral levels, tumor mass and Ki67 index) following s.c. inoculation of Scr, or MCF-7 ALDH1A1+ or MCF-7 ALDH1A1KD tumor cells, provided results comparable to those obtained in vitro." (PMID 30541574, 2018). "In conclusion, CD44v6 and ALDH1A1 are candidate stem cell markers for NPC, and the increased formation of DNA lesions by inflammation may result in the mutation of stem cells, leading to tumor development in NPC." (PMID 27647953, 2016). "In addition, greater possibility of LNM and higher expression of HER2 could be found in America-Europe patients with high ALDH1A1 expression in tumor." (PMID 24938375, 2014). "Positive correlations between ALDH1A1 enzyme activity and expression are apparent, indicating that ALDH1A1 expression or activity may be used with other cell surface markers to identify tumor-initiating cells in hepatocellular, prostate and breast solid carcinomas." (PMID 22852552, 2012). "In this study, FABP4, PPARGC1A, AGPAT4, ALDH1A1, and GPAT3 were identified as downregulated tumor suppressor genes in TC, whereas TGFA was recognized as an oncogene." (PMID 40119647, 2025). "Numerous studies have demonstrated a significant correlation between aldehyde dehydrogenase 1 family member a1 (ALDH1A1) expression and various clinicopathological factors in BC, including tumor size, nodal status, histological grade, and BC subtypes." (PMID 40923026, 2025). "Lately, Wang et.al found that ALDH1A1 enhances the transcriptional regulation of LDHA by ZBTB7B, leading to increased lactate production and reduced anti-tumor immune cell infiltration." (PMID 39897050, 2025). "Our clinical data further validate this, showing that ALDH1A1 expression is upregulated in NSCLC tissues and significantly correlates with tumor prognosis, progression, and distant metastasis." (PMID 40886002, 2025). "Specifically, ALDH1A1 exhibited reduced expression in the tumor group, whereas S100A4 levels were increased in the tumor group." (PMID 40093000, 2025).
tumor (continued). "Many molecules have been proposed as markers (ALDH1a1, ABCG2, CD44, CD133, CD271, NANOG), but they are also found in non-tumor stem cells and normal melanocytes." (PMID 40806546, 2025). "Further, the combination of ALDH1A1 inhibitor CM2 and PD-1 mAb represents a promising therapeutic strategy to mitigate tumor immune escape." (PMID 39897050, 2025). "Analysis of the expression levels of ALDH1A1 and S100A4 in each tumor cell subset revealed that the chemoresistant tumor cell subset exhibited elevated levels." (PMID 40093000, 2025). "Our study identified a correlation between ALDH1A1 and S100A4 with up-regulated immune and metabolic pathways in the resistant subgroup, alongside the enrichment of certain tumor and glucose metabolism-related pathways." (PMID 40093000, 2025). "The elevated lactylation levels of ALDH1A1 and S100A4 in tumor cell subgroups from the resistant group indicate that the lactylation of these genes is significant in the development of drug resistance." (PMID 40093000, 2025). "For example, disrupting the binding of KK-LC-1 to FAT1 can lead to a reduction in ALDH1A1 transcription, which reduces ALDH + cell stemness and viability and ultimately leads to the inhibition of TNCB tumour growth." (PMID 38916835, 2024). "To investigate the role of ALDH1A1 and ALDH1A3 for tumor cell survival in the bloodstream and during the extravasation process in vivo, we employed the larval zebrafish (Danio rerio) model to xenograft human prostate cells." (PMID 38169509, 2024). "The levels of ALDH1A1 and BMP4 were also high in the METABRIC miR-18a/low tumours on analysis of the DEGs (p < 0.05)." (PMID 38786043, 2024). "LIFR silencing markedly impaired tumor formation and decreased CSCs frequency in vivo, accompanied by diminished SOX2, CD44 and ALDH1A1 expression in samples." (PMID 39206755, 2024). "CSCs showed high expression of stem cell marker genes such as PROM1, ALDH1A1, and SOX4, and increased the activity of tumor-related hypoxia, Wnt/β-catenin, and Notch signaling pathways." (PMID 39107908, 2024). "In our study, we identified four key genes (ALDH1A1, ASAH1, CDT1, and CDC45) that affect tumor cell stemness and lymph node metastasis." (PMID 38589907, 2024). "According to other sources, the expression of ALDH1A1 relates to a favorable prognosis, less advanced FIGO stage, better tumor differentiation, and better survival rates." (PMID 36768723, 2023). "Immunohistochemical analysis confirmed the expression of ALDH1A1, CD44, and EpCAM in both TN and NAT tumor tissues." (PMID 36400567, 2023). "The stimulation of CD8+ T cells with ALDH1A1 peptide-pulsed APC recognized and eliminated the ALDHhigh CSCs and inhibited tumor growth and metastases in various solid tumors, including BC." (PMID 37251931, 2023). "ALDH1A1 and CD133 positivity was only identified in tumor cells, while CD44 was present in tumor cells and tumor-surrounding stroma cells." (PMID 36768723, 2023). "Similarly, the downregulation of ALDH1A1 and GSTA, protecting cells from reactive oxygen species, could describe a condition with reduced detoxification capacity and increased susceptibility to oxidative stress, which in turn promote tumor growth and survival." (PMID 37686696, 2023). "Decreased expression of BCSC stemness regulators ALDH1A1 and SOX2 were observed in the tumor spheres treated with Z8." (PMID 37147285, 2023). "Treatment with the BTK inhibitor AVL-292 also reduced tumor sphere formation in HNSCC-derived cell lines and the expression of the stemness marker ALDH1A1." (PMID 37685940, 2023). "The expression level of ALDH1A1 and CFD was significantly higher in the tumor group compared with the normal group." (PMID 37359050, 2023). "Although ALDH inhibitors have a potential to diminish ALDH1A1 expression within the cell, ATRA treatment can increase the tumor proliferation potential." (PMID 37645246, 2023).